OAS1 (2'-5'-oligoadenylate synthetase 1)
Diseases named in the same sentence as OAS1 in open-access papers (continued):
Sharing a sentence is not in itself a finding about the gene and the disease.
cancer (continued). "In our study, we conducted a pan-cancer investigation of the OAS1 gene, employing bioinformatic analyses and integrating data from multiple databases." (PMID 37928544, 2023). "In summary, OAS1 is differentially expressed in pan-cancers and is correlated with patient prognosis." (PMID 37746262, 2023). "We stratified cancer patients based on their OAS1 CNV levels and found that high OAS1 CNV levels were associated with shorter survival rates in COAD (HR=2.24, p = 0.001) and LUAD (HR=1.92, p=0.037)." (PMID 37928544, 2023). "Radar plots revealed that OAS1 expression was positively correlated with TMB in four cancers (KIRC, LGG, PAAD, STAD) and with MSI only in KIRC." (PMID 37928544, 2023). "Increased OAS1 expression in cancer cells promotes their ability to survive DNA damage by attenuating Poly(ADP-ribose) synthesis and thus preventing cell death." (PMID 35804895, 2022). "And the high expression of OAS1 in cancer cells prevents cell death by inhibiting PAR synthesis and promotes their ability to survive DNA damage." (PMID 35898870, 2022). "The high expression of OAS1 promotes the ability of cancer cells to survive DNA damage by reducing PAR synthesis, thus preventing cell death." (PMID 36030212, 2022). "Our study found that many OAS1-related pathways are involved in the development and progression of cancer." (PMID 35898870, 2022). "Then, we constructed a prognostic index for all cancer samples calculated by the formula IRGRS = expression level of EGFR*0.228279845567824 + expression level of OAS1*(-0.264868237274861)+expression level of MST1R*(-0.167523923476614)." (PMID 36267410, 2022). "IL6 was particularly upregulated in murine cancer cells, while OAS1 was significantly upregulated by human cancer cells." (PMID 35937459, 2022). "Among the enriched CCs, The cytoplasm (associated with 6 KGs: OAS1, OAS3, IRF9, HPGD, TP53INP1 and NQO1) has been found to be associated with most proteins that are highly expressed for cancer." (PMID 35617355, 2022). "We also proposed that OAS1 expression enhancement can induce the anti-cancer effects of interferon-gamma, while suppression of CTSH hinders formation of focal adhesions." (PMID 34249670, 2021). "Rs4801778-T (PLEKHA4), rs11919389-C (ZBTB11), rs13050728-C (IFNAR2), and rs10774671-A (OAS1) exhibited a positive or negative regulation in TULP2, HSD17B14, LOC285359, LOC100009676, SENP7, IFNAR2, OAS3, and OAS1 in multiple cancer types." (PMID 35082790, 2021). "In support of this concept is a recent and growing appreciation for OAS1-mediated translational control in cell cycle control, adipocyte differentiation and the role of RNase L in certain types of cancers." (PMID 25477390, 2015). "A study employed bioinformatics methods to explore the role of OAS1 in pan-cancer." (PMID 41584451, 2025). "Interestingly, pan-cancer analysis has revealed significant differential expression of OAS1 across various tumors." (PMID 40055311, 2025). "To identify other components of IFN signaling in GBMs, we identified 100 genes whose expression presented the highest correlation to OAS1 (Spearman’s r > 0.55; q value < 5.0E-12) in The Cancer Genome Atlas (TCGA) GBM data set (CBIOPortal, accessed on 01/19/24)." (PMID 39919036, 2025). "Previous studies have reported that OAS genes, particularly OAS1 and OAS3, are often involved in antiviral responses and immune regulation but have not been extensively studied for their mutational frequency in cancers." (PMID 39633486, 2024). "Notably, CD96 exhibited significant predictive ability for OS in 9 cancers (all P < 0.05), CSH1 demonstrated significance in 3 cancers (all P < 0.05), and OAS1 emerged as a significant predictor in 10 cancers (all P < 0.05)." (PMID 38566204, 2024). "Overall, our results suggest that OAS1 may play an oncogenic role in various tumors, and its clinical application value is worth exploring at the pan-cancer level." (PMID 37928544, 2023).
cancer (continued). "We used the TIMER 2 database to analyze the expression level of OAS1 in pan-cancer." (PMID 37746262, 2023). "Furthermore, almost all cancers demonstrated a positive correlation between OAS1 expression and GSVA scores of the interferon-γ signaling pathway and IL6-JAK-STAT3 signaling pathway." (PMID 37928544, 2023). "Unfortunately, this study did not investigate differences in the OAS1 SNP polymorphism in pan-cancers and its impact on patient prognosis." (PMID 37746262, 2023). "Furthermore, we investigated the impact of copy number variations (CNVs) in the OAS1 gene on the prognosis of cancer patients." (PMID 37928544, 2023). "OAS1 is primarily expressed in cancer cells and macrophages as a member of the ISG.RS." (PMID 37928544, 2023). "However, the mechanism by which OAS1 affects tumors is unclear and pan-cancer study of OAS1 is necessary to better understand its implication in cancers." (PMID 37928544, 2023). "To investigate the biological processes and molecular mechanisms of OAS1 regulation in pan-cancer, we identified a gene-sets including top200 genes that positively co-expressed with OAS1 using GEPIA database, which were used to perform GSEA and KEGG annotation analyses." (PMID 37746262, 2023). "Furthermore, we observed that after the OAS1 gene is methylated, the prognosis of cancer patients significantly improves." (PMID 37928544, 2023). "However, there is an extreme paucity of information on the role of OAS1 in regulating a cancer phenotype." (PMID 37686559, 2023). "We found an inconsistent expression of OAS1 expression in pan-cancer." (PMID 37746262, 2023). "Our above data suggest that OAS1 may be involved in the immune response in pan-cancer, which indicated that OAS1 might be involved in antitumor immune response." (PMID 37746262, 2023). "In addition, we investigated the impact of OAS1 on genomic stability, methylation status, and other factors across different types of cancer, and the effects of these factors on prognosis." (PMID 37928544, 2023). "In this study, we applied bioinformatics methods to explore the role of OAS1 in pan-cancer." (PMID 37746262, 2023). "OAS1, initially identified as an interferon-induced antiviral enzyme, was recently associated with 5-azacytidine (AZA) sensitivity, the deficiency of which resulted in the NCI-60 set of cancer cell lines resistant to AZA." (PMID 33685397, 2021). "Expression of OAS1 is induced by interferons against cancers." (PMID 32226026, 2020). "Furthermore, OAS1 may be regulated by 17β-estradiol (E2) and play a crucial role in inducing apoptosis in cancer cells." (PMID 41584451, 2025). "However, despite progress in understanding the association of OAS1 with select cancers, no pan-cancer analysis has yet been performed to examine its potential use as a biomarker or therapeutic target." (PMID 37928544, 2023). "In addition, OAS1 may be regulated by 17β-estradiol (E2) and play a key role in inducing apoptosis in cancer cells." (PMID 35898870, 2022). "In addition, OAS1 expression is negatively correlated with the progression of these cancers." (PMID 34249670, 2021). "Our transcriptomic analyses of CM-treated HOSEs uncovered gene-expression profiles defining responses to cancer-like TME, highlighted by STAT1, ISG15, and OAS1 in HOSE1C and ITGA2, GREM1, and CDH13 in HOSE2C." (PMID 39634630, 2024). "Our analysis revealed that the lower OAS1 expression group exhibited a notable increase in the infiltration of CD8+ T cells and displayed enhanced cytotoxic effects on cancer cells, compared to the group with higher OAS1 expression." (PMID 37928544, 2023). "We analyzed the transcription level of OAS1 in pan-cancer based on TIMER, TCGA databases, and also using the CPTAC and HPA databases to explore the protein level of OAS1." (PMID 37746262, 2023). "In IDC, we found that the mRNA levels of OAS1 and STAT1 were downregulated, which has also been reported in other cancers." (PMID 36765396, 2023).
cancer (continued). "We also analyzed the mRNA expression of OAS1 and IFI27 in tissue samples from 26 CRC cancer tissues and 10 normal colon tissues." (PMID 36458816, 2022). "We also found that MUC1-C is necessary for the expression of IFN-stimulated genes (ISGs), including IFIT1/3, OAS1/3, IFITM1, IFI44L and MX1, that promote DNA damage resistance, chronic inflammation and cancer progression." (PMID 34657147, 2022). "The expression of TF-protein FOXL1 (a regulator of NT5E, TP53INP1, HPGD, FN1, OAS1 and NQO1) is connected with numerous cancer." (PMID 35617355, 2022). "In particular, the expression levels of genes, such as IFI6, MX1, IFIT1, IFIT3, ISG15, OAS1, and OAS2, which belong to the cancer-promoting ISG subset IRDS, were markedly increased." (PMID 35618021, 2022). "Of the eight modeling RBPs, half were upregulated including PABPC1, PRPF6, OAS1, IPO7, and half were downregulated including RBM5, RBM6, LSM12, and FXR7 in cancer cases." (PMID 33584809, 2020). "To date, the expression level and role of OAS1 in most tumors are still unclear, and a comprehensive analysis of the functional and clinical significance of OAS1 at the pan-cancer level has not yet been performed." (PMID 37746262, 2023). "In several cancers, such as LIHC (p = 0.020), COAD (p = 0.022), UCEC (p < 0.001), BLCA (p = 0.035), BRCA (p = 0.024), and LUAD (p = 0.034), high expression of OAS1 diminishes or even reverses the benefits of CTL infiltration levels on patient survival." (PMID 37928544, 2023). "As a result, MUC1-C was also necessary for expression of (i) OAS1, which attenuates PAR synthesis during DNA repair and promotes the ability of cancer cells to survive replicative stress, and (ii) IFIT1-3, MX1 and BST2, among others, which confer DNA damage resistance." (PMID 35681561, 2022). "Given the well-established role of OAS1 in antiviral defense mechanisms and immune modulation, its pleiotropic effects may extend beyond CRC to systemic inflammatory processes that contribute to both cancer and cardiovascular diseases." (PMID 40303978, 2025).
infectious disease (5 papers, 2015 to 2023). A disorder directly resulting from the presence and activity of a microbial, viral, or parasitic agent in humans. "Given the importance of the OAS1 protein, SNPs in the OAS1 gene may affect susceptibility to infectious diseases." (PMID 30497421, 2018). "Notably, three genes, OAS1, OAS2, and OAS3 of the 2'-5'-oligoadenylate synthetase family, were significantly up-regulated in T2DM and presented in all of these infectious disease pathways." (PMID 28427244, 2017).
bacterial infection (3 papers, 2020 to 2025). "It has been established that the presence of full-length OAS1 within THP-1 cells enhances their resistance to bacterial infection." (PMID 41099523, 2025). "Furthermore, we analyzed the mRNA expression of molecules that are involved in the induction of the type-I-IFN signaling (RIG-I, IFN-β, MxA, and OAS1), since it was described that IV-induced type-I-IFN signaling had an impact on bacterial infections." (PMID 33333815, 2020).
immune diseases (2 papers, 2015 to 2023). "Studies have shown that the changes of OAS1 can also be used as a basis to determine the course of some immune diseases." (PMID 37746262, 2023). "Specifically, eight genes (IRF5, UBA7, TMTC1, GSTM3, FBN2, OAS1, PODXL, ITGA2) were previously associated with immune system diseases in at least one study." (PMID 25874939, 2015).
colon polyps (1 paper, 2025). "Colocalization analysis confirmed strong shared association signals between BET1L and OAS1 in CRC and colon polyps, supporting their pleiotropic effects in colorectal neoplasia." (PMID 40303978, 2025). "We identified 25 genome-wide significant loci for CRC and colon polyps, including three novel loci in East Asian populations: BET1L (rs12226698, 11p15.5), OAS1 (rs2525858, 12q24.13), and BMP2 (rs4813802, 20p12.3)." (PMID 40303978, 2025). "In this analysis of CRC and colon polyps, we identified 25 genome-wide significant loci, including three novel loci in East Asian populations: rs12226698 at 11p15.5 (BET1L), rs2525858 at 12q24.13 (OAS1), and rs4813802 at 20p12.3 (BMP2)." (PMID 40303978, 2025).
inflammatory myopathies (1 paper, 2023). "Using microarrays, IFIG expression levels (including ISG5, Mx1, OAS1, IFIT4, IFIT1, IFI44, OAS3, OAS2, IRF7, and IFI27) in muscle samples were higher in DM than in other inflammatory myopathies, such as inclusion body myositis, polymyositis, necrotizing myopathy, and myopathies with inflammation." (PMID 36979843, 2023). "In addition, the IFN6 score (ISG15, LY6E, IFI44, IFI27, IFIT1, and OAS1) was higher in 13 DM patients than in 40 patients with inflammatory myopathies (no patients had SLE or MCTD)." (PMID 36979843, 2023).
metabolic disorders (1 paper, 2022). "Therefore, the use of belimumab and targeted therapy against OAS1 may help restore monocyte metabolic dysfunction and further alleviate the metabolic disorder in SLE patients." (PMID 36341378, 2022). "Thirdly, the exact mechanisms of metabolic disorders mediated by TNFSF13B and OAS1 and their exact relationship with monocytes need further investigation." (PMID 36341378, 2022).
OAS1 also shares sentences with these, for which no sentence is quoted: asthma (5 papers); multiple sclerosis (4); rheumatoid arthritis (3); cervical carcinoma (2); cholangiocarcinoma (2); chronic lymphatic leukaemia (2); Crohn disease (2); dermatitis (2); discoid lupus erythematosus (2); endometrial cancer (2); inflammatory bowel disease (2); lymphoma (2); psoriatic arthritis (2); Sepsis (2); viral disease (2); adenoma (1); alveolar proteinosis (1); Arthritis (1); autoinflammatory syndrome (1); cardiovascular diseases (1); chronic leukemia (1); chronic obstructive pulmonary disease (1); Cognitive impairment (1); diabetic kidney disease (1); dry eye syndrome (1); emphysema (1); Epstein-Barr virus infection (1); Esophageal carcinoma (1); familial hypercholesterolemia (1); foot and mouth disease (1).
A further 36 diseases each share a sentence with OAS1 in 1 paper.